AMIGO1 (adhesion molecule with Ig like domain 1)
Description:
Promotes growth and fasciculation of neurites from cultured hippocampal neurons. May be involved in fasciculation as well as myelination of developing neural axons. May have a role in regeneration as well as neural plasticity in the adult nervous system. May mediate homophilic as well as heterophilic cell-cell interaction and contribute to signal transduction through its intracellular domain.
Synonyms: ALI2; AMIGO; KIAA1163; AMIGO-1
Tractability: Antibody: UniProt places it where antibodies can reach, with medium confidence; UniProt predicts a signal peptide or a membrane-spanning region; its Gene Ontology location is reachable by antibodies, with medium confidence. PROTAC: ubiquitination databases record sites on it; its protein half-life has been measured.
Gene: Protein-coding gene on chromosome 1 (109,504,178 to 109,509,738, reverse strand). Ensembl gene ENSG00000181754.
Subcellular location: Cell membrane; Perikaryon; Cell projection, dendrite; Cell projection, axon
Subcellular location (Human Protein Atlas): Vesicles
Gene Ontology:
Molecular function: protein binding; potassium channel regulator activity
Biological process: axonal fasciculation; brain development; heterophilic cell-cell adhesion; homophilic cell-cell adhesion; myelination; positive regulation of axonogenesis; positive regulation of potassium ion transmembrane transport; positive regulation of synapse assembly; axonogenesis; cellular response to L-glutamate; neuron projection fasciculation; positive regulation of cation transmembrane transport; positive regulation of neuron projection development
Cellular component: dendrite; membrane; neuronal cell body membrane; voltage-gated potassium channel complex; axon; neuron projection; neuronal cell body; pericellular basket; perikaryon; plasma membrane
Genetic constraint (gnomAD): Loss-of-function variants: 0 observed, 30.16 expected, observed/expected ratio (o/e) 0, 90% interval 0 to 0.099. The upper end of that interval is the gene's LOEUF score, 0.099, which puts it in group 1 of 6, group 1 being the genes least tolerant of losing a copy. Missense variants: 361 observed, 643.88 expected, observed/expected ratio (o/e) 0.56, 90% interval 0.51 to 0.61. Synonymous variants: 249 observed, 282.54 expected, observed/expected ratio (o/e) 0.88, 90% interval 0.79 to 0.98.
Homologues: Orthologues: chimpanzee AMIGO1 (100% identical), macaque AMIGO1 (100% identical), dog AMIGO1 (96% identical), pig AMIGO1 (94% identical), rabbit AMIGO1 (92% identical), guinea pig AMIGO1 (91% identical), mouse Amigo1 (89% identical), rat Amigo1 (89% identical), tropical clawed frog amigo1 (56% identical), zebrafish amigo1 (39% identical). Paralogues in human: AMIGO2 (41% identical), AMIGO3 (36% identical).
Diseases named in the same sentence as AMIGO1 in open-access papers:
AMIGO1 is named in the same sentence as 11 diseases in open-access papers, as found by Europe PMC text mining. Sharing a sentence is not in itself a finding about the gene and the disease. The quoted sentences say what the papers report.
schizophrenia (2 papers, 2022 to 2025). A major psychotic disorder characterized by abnormalities in the perception or expression of reality. "AMIGO1, a neuronal cell‐adhesion protein affecting neurite growth, fasciculation, and myelination is also associated with schizophrenia." (PMID 40665476, 2025). "AMIGO1 knockout mice display schizophrenia-related features, and AMIGO1 knockdown zebrafish have deformed neural tracts." (PMID 35314141, 2022). "AMIGO1 has been proposed to play a role in schizophrenia biology." (PMID 35314141, 2022).
viral infection (2 papers, 2021 to 2024). "In mice with global AMIGO1 deletion or AMIGO1 deletion in individual HCs via viral infection, the HC axonal arbor size shrinks, leading to mislamination into the outer nuclear layer (ONL), but HC dendrites and soma distribution remain unchanged." (PMID 39292551, 2024). "One possible interpretation of this under-expression of ZC3H13 and AMIGO1 in COVID-19 that could be investigated in future studies is that this novel virus may be inhibiting their expression to escape the host responses that are otherwise functional for previously circulating viral infections." (PMID 33437935, 2021).
Anxiety (1 paper, 2025). Intense feelings of nervousness, tension, or panic often arise in response to interpersonal stresses. "Using a chemogenetic approach to specifically target Amigo1-expressing or Epyc-expressing neurons within the IPN, we found that activity of the Amigo1 subpopulation of GABAergic neurons is critical for anxiety-like behaviors both in naïve mice and in those undergoing nicotine withdrawal." (PMID 41443382, 2025).
COVID-19 (1 paper, 2021). A disease caused by infection with severe acute respiratory syndrome coronavirus 2. "Since the “COVID-19-specific gene signature” is derived from direct comparison of COVID-19 versus non-COVID-19 infections, ZC3H13, AMIGO1, and ATL3 under-expressed in COVID-19 equates to higher expression in non-COVID-19 infections." (PMID 33437935, 2021).
metabolic syndrome (1 paper, 2025). A cluster of metabolic risk factors for CARDIOVASCULAR DISEASES and TYPE 2 DIABETES MELLITUS. "AMIGO1 (delayed‐recall) and ZPR1‐APOA5 (metabolic syndrome) exhibit distinct haplotype structure compared to other populations." (PMID 40665476, 2025).
multiple sclerosis (1 paper, 2021). A progressive autoimmune disorder affecting the central nervous system resulting in demyelination. "AMIGO1 was shown to be down-regulated in the post-mortem multiple sclerosis brain as well." (PMID 34768988, 2021).
tumor (2 papers, 2022 to 2026). "The results indicated that AMIGO1 expression was significantly associated with tumor stage, suggesting its potential role in the progression of PAAD." (PMID 41583520, 2026). "In contrast, AMIGO1 and AMIGO3 have not been consistently associated with tumor aggressiveness or adverse prognosis in these settings and do not exhibit robust expression changes in PAAD." (PMID 41583520, 2026).
AMIGO1 also shares sentences with these, for which no sentence is quoted: cancer (1 paper); infection (1); ischemia (1); pancreatic adenocarcinoma (1).